SYP (synaptophysin)
Diseases named in the same sentence as SYP in open-access papers (continued):
Sharing a sentence is not in itself a finding about the gene and the disease.
diabetes (continued). "Caffeine consumption attenuated the diabetes-induced decrease of SNAP25 and synaptophysin immunoreactivity, whereas it was devoid of effects in control mice." (PMID 22514596, 2012). "Synaptophysin mRNA translation was significantly increased after 1 month (p<0.001) and 2 months (p<0.05) of STZ-diabetes, compared to age-matched controls." (PMID 22970294, 2012). "The presynaptic proteins synaptophysin, synapsin 1, VAMP2, SNAP25, and PSD95 all show decreases after only one month of diabetes, especially when synaptosomal fractions are selectively examined." (PMID 19936028, 2009). "Twenty-four weeks post-diabetes, the mice showed a significant reduction in the expression of synaptophysin in the retina when compared to the non-diabetic controls (p < 0.05)." (PMID 39768141, 2024). "Therefore, we assessed the effects of diabetes on the expression of FOXO-regulated memory-related genes, including SYP, BDNF, and PAX7 genes in the cerebellum." (PMID 37970442, 2023). "Furthermore, it was observed that the diabetes- mediated suppression of PSD95, synaptophysin and synapsin-1 expressions in hippocampus were markedly reversed by GSK treatment, which is consistent with those in FGF1-treated group." (PMID 32460803, 2020). "In order to analyze the effect of experimental diabetes and EE on retinal synapses, synaptophysin immunoreactivity was analyzed in retinas from non-diabetic and diabetic animals housed in SE or EE." (PMID 25004165, 2014). "The mechanism by which the PARP inhibitor prevents diabetes-induced changes in the expression of BDNF, synaptophysin, GS, and caspase-3 in the retinas remains unclear." (PMID 24347828, 2013). "Administration of 1,5-isoquinolinediol did not affect the metabolic status of the diabetic rats, but it significantly attenuated diabetes-induced upregulation of PARP, ROS, ERK1/2 phosphorylation, and cleaved caspase-3 and downregulation of BDNF, synaptophysin, and GS." (PMID 24347828, 2013). "Diabetes and intravitreal administration of HMGB1 induced significant upregulation of the expression of HMGB1, TBARS, and cleaved caspase-3, whereas the expression of BDNF and synaptophysin was significantly downregulated in rat retinas." (PMID 23766563, 2013). "However, in lutein-administered mice, in which the synaptophysin and BDNF levels are preserved after 1 month of diabetes, the thickness is preserved, and the neuronal cells survive by constant treatment." (PMID 22144984, 2011). "However, our findings suggested that inhibition of PARP that attenuates diabetes-induced changes in the expression of BDNF, synaptophysin, GS, and caspase-3 could be mediated by attenuating ROS generation." (PMID 24347828, 2013). "After 4 weeks of diabetes, the retinas were harvested and the levels of reactive oxygen species (ROS) were determined fluorometrically and the expressions of PARP, phosporylated-ERK1/2, BDNF, synaptophysin, glutamine synthetase (GS), and caspase-3 were determined by Western blot analysis." (PMID 24347828, 2013). "The increase in endo H sensitive synaptophysin after 1-month of diabetes could explain the accelerated degradation of 35S-synaptophysin at this time point; however the lack of change in endo H-sensitive synaptophysin in the retinas of 2-month diabetic rats does not." (PMID 22970294, 2012). "In addition, GA attenuated diabetes-induced upregulation of cleaved caspase-3 and glutamate and counteracted the downregulation of synaptophysin, TH, GS, and GLO1 induced by diabetes without changing body weight or blood glucose levels." (PMID 24733965, 2014).
depression (27 papers, 2018 to 2025). "Animal models of depression illustrated a reduction in the expression level of synaptic proteins such as synaptophysin which regulates synapse formation and its expression precisely reflects synaptic density." (PMID 40100376, 2025). "Uniquely, the decrease in CNPase and synaptophysin in the white matter mediate an impairment of synaptic potentiation and in anxiety and depression, alongside the upregulation of HCN1 and downregulation of KCNQ3 in the amygdala." (PMID 39851502, 2025). "Depression animal model revealed the reduction in expression levels of synaptophysin in prefrontal cortex and hippocampus." (PMID 40100376, 2025). "Meneses-San Juan and coworkers found that four weeks of 5 Hz rTMS in a female mouse depression model increased synaptophysin (SYP), histone H3 trimethylation, and reversed stress-induced global DNA hypomethylation." (PMID 41440017, 2025). "The abnormal expression levels of functional proteins are closely related to depression susceptibility, including brain-derived neurotrophic factor (BDNF), postsynaptic density 95 (PSD-95), synaptophysin (SYN), and protein kinase M zeta (PKMZ)." (PMID 37179843, 2023). "Expression of different monoamine receptor subtypes, e.g., dopamine D1 and D2, and synaptic vesicle release-regulating proteins, e.g., synaptophysin, is altered under conditions of stress and depression." (PMID 35928261, 2022). "Synaptophysin was downregulated in the rats with depression-like phenotype but upregulated in the rats with anxiety-like phenotype." (PMID 30740068, 2018). "Furthermore, synaptic integrity was compromised, as indicated by a significant decline in synaptic protein SYP levels, aligning with previous findings on synaptic dysfunction in depression." (PMID 40092064, 2025). "Multiple aspects of these processes are implicated in the development of anxiety and depression in CCH, including aberrant GABA and glutamate signaling, reduced BDNF, impaired synaptic potentiation, changes in synaptophysin, serotonin, and HCN1, as well as reduced dopamine and KCNQ3 activity." (PMID 39851502, 2025). "To further examine whether synapse-localized C3 contributed to synapse loss in depression, we stained microglia (Iba1), postsynapse (PSD95), or presynapse (synaptophysin) in the prefrontal cortex." (PMID 35715851, 2022). "On the other hand, Xiaoyao pills could reduce the level of inflammatory cytokines, enhance the expression of neurotrophic factors and synaptophysin to inhibite the behavior abnormality of LPS-induced depression-like model rats." (PMID 36569324, 2022). "The severity of depressive disorder is known to correlate inversely with the synapses density in the prefrontal cortex and hippocampus, while the synapses density correlates with the synaptophysin level." (PMID 33578683, 2021). "In addition, synaptophysin was downregulated in the rats with depression-like phenotype but upregulated in the rats with anxiety-like phenotype." (PMID 30740068, 2018). "The expression of brain-derived neurotrophic factor (BDNF), synaptophysin (SYN), and postsynaptic density 95 (PSD95) is closely related to the regulation of neuroplasticity, especially synaptic changes in depression." (PMID 39852377, 2025). "In regards to synaptic plasticity, specific neurobiological mechanistic targets for anxiety and depression include transforming growth factor β, BDNF, glycogen synthase kinase-3β, synaptophysin, and lipid peroxidation." (PMID 39851502, 2025). "Large evidence postulates that expression of PSD‐95 and SYP in the HIPP of rats with depression are decreased; conversely, increasing PSD‐95 and SYP in the HIPP alleviated depressive symptoms." (PMID 38553964, 2024). "Studies have shown that increasing the levels of synaptophysin and PSD95 in the hippocampus of mice can help alleviate depression-like behaviors." (PMID 39263574, 2024).
depression (continued). "Among the regulated genes in neuronal cell lines were synapsin, synaptophysin, Crh, BDNF, and the serotonin 1A receptor, which are highly relevant for depression and antidepressant response." (PMID 34972135, 2021). "As a result of the H2S-dependent upregulation of the mTORC1/TrkB signaling pathway, the expression of synaptic proteins, such as PSD-95, synaptophysin, and the AMPA receptor GluR 1/2 subunit, in the hippocampus of rats with depression-like behavior, was increased." (PMID 37445920, 2023). "This means that brain-derived IL-34, SYP, and TNFR1 might be related to depression-like behaviour and depression symptoms." (PMID 36970289, 2023). "CX3CR1CreERIL-10 knockout mice exhibited depression- and anxiety-like behaviors, along with decreased NR2B (N-methyl-D-aspartate receptor (NMDAR) subunit) and synaptophysin (SYP) levels in the mPFC, and increased NR2B and postsynaptic densitin-95 (PSD95) levels in the amygdala." (PMID 35668399, 2022). "Furthermore, a plethora of studies showed that the PTEN/AKT/mTOR or BDNF/synaptophysin pathway was not changed in a variety of depression models compared to that of the control group." (PMID 36969556, 2023).
neuroblastoma (27 papers, 2014 to 2025). Neuroblastoma (NB) is the most common solid, extracranial childhood tumor. "Gene expression of markers distinctive for differentiated neurons, such as microtubule-associated protein 2 (MAP2) and synaptophysin (SYP), indeed confirmed that MRx0029 induced a differentiated phenotype in neuroblastoma cells." (PMID 31619962, 2019). "This study indicated that synaptophysin could be an important diagnostic marker for evaluating neuroblastoma and should be included in marker panels." (PMID 36230740, 2022). "Neuroblastoma often shows synaptophysin and chromogranin, while desmoplastic small round cell tumors co-express cytokeratins and desmin." (PMID 40084340, 2025). "Pathologic examination revealed sheets of small round blue cells positive for chromogranin, synaptophysin, and cluster of differentiation 56, establishing the diagnosis of neuroblastoma." (PMID 40201045, 2025). "The xenograft tumors arising from injected Lan-5 control cells were homogenous in morphology, exhibited high nuclear to cytoplasmic ratio, and were confirmed to be neuroblastomas by immunohistochemical staining for the neuroblastoma marker synaptophysin." (PMID 38413795, 2024). "The fact that this strong synaptophysin is indicative of the neuroendocrine characterization common among neuroblastomas." (PMID 38234938, 2023). "We have shown that the tumors that arise in the IRG in this transgenic fish model are small, round, blue cell tumors expressing tyrosine hydroxylase and synaptophysin, which are markers of human neuroblastoma." (PMID 37183825, 2023). "SH-SY5Y neuroblastoma cells differentiate into more mature, neuron-like phenotype cells with increased electrical excitability of the plasma membrane and synaptophysin-positive functional synapses." (PMID 35630814, 2022). "The highest percentage of synaptophysin-positive cells was observed with serum-free medium, a medium developed for the culture of neuroblastomas, whereas ‘Izal’ medium harboured the lowest relative percentage of synaptophysin and GFAP-positive cells." (PMID 36178902, 2022). "We further analysed the expression of differentiation-related genes (SYP, NEFL, ENO2, MAPT) in high-risk neuroblastoma patients and correlated them to HIF1A expression." (PMID 34557995, 2022). "In a study evaluating the utility of synaptophysin for detecting childhood neuroblastoma, synaptophysin immunoreactivity was found in six of six neuroblastoma samples tested but not in other small round cell tumors with similar features." (PMID 36230740, 2022). "Although viewed as a marker of neuronal synaptic vesicles, synaptophysin protein (SYP) was identified in medulloblastoma, neuroblastoma, and other tumors more than 30 years ago." (PMID 32292341, 2020). "These 3D spheroids retain expression of neuroblastoma markers chromogranin A, synaptophysin and tyrosine hydroxylase and retain their tumorigenic and spontaneous metastatic capacity upon orthotopic injection." (PMID 28924803, 2018). "PHOX2B, a highly specific marker for neuroblastic tumors, exhibited strong nuclear staining across all primary cultured human neuroblastoma cells, while synaptophysin staining revealed clear cytoplasmic patterns, facilitating individual tumor cell identification." (PMID 40552293, 2025). "In contrast, the small amount of tissue recovered at the injection site of mice injected with AF1q-silenced Lan-5 cells was mostly comprised of acellular material with sparse detectible cells that were also positive for synaptophysin and presumed to be neuroblastoma xenograft." (PMID 38413795, 2024). "Immunohistochemistry of neuroblastoma tumours demonstrates that (i) synaptophysin is constitutively expressed by neuroblastoma tumoural cells, (ii) NEFL gene mutation is common yet inefficient in neuroblastoma tumours, and (iii) neuron-specific enolase (ENO2) is a non-favourable marker." (PMID 34557995, 2022).
neuroblastoma (continued). "A neural-lineage promoting role for MYCN is very interesting in the context of the neuroblastoma histologic phenotype, where even poorly differentiated tumors show diffuse reactivity for the neural marker synaptophysin, and truly “undifferentiated” tumors are rare." (PMID 26222553, 2015). "Indeed, pathological features can overlap between embryonal tumor subtypes, particularly those with BRD4::LEUTX fusions and FOXR2-activated neuroblastomas; most notably the small poorly differentiated cells, abundant necrosis, and co-expression of immunomarkers synaptophysin and OLIG2." (PMID 38500181, 2024). "According to the study of Yin and colleagues in 201530, asiaticoside, which is the other major active constituent of ECa 233, also promoted the expression of p-Akt, GSK-3, synaptophysin (SYN) and PSD-95 in high glucose-treated neuroblastoma cells." (PMID 31182820, 2019). "Analysis of genes that are increased with retinoic acid induced differentiation of neuroblastoma cells (NGRF, NF68, NTRK1, SYP, MAP2, NEFM, DKK2) showed that all were elevated after 72 hours Wnt3a/Rspo2 treatment." (PMID 29505958, 2018). "Ewing sarcoma expresses CD99 in 90 % of cases and is differentiated from neuroblastoma by the finding of negative synaptophysin." (PMID 39383765, 2024). "On immunohistochemical staining, the xenografts were variably positive for commonly used neuroblastoma diagnostic markers NB84 and CD56 (centre and right panels), and synaptophysin (not shown)." (PMID 31919402, 2020). "Blastemal type WTs and neuroblastomas are both positive for CD56, but WT1 is negative in neuroblastoma, while synaptophysin, chromogranin A, NB84, and PHOX2B are positive in neuroblastoma." (PMID 32204536, 2020).
schizophrenia (25 papers, 2011 to 2025). A major psychotic disorder characterized by abnormalities in the perception or expression of reality. "Our findings of reductions in synaptophysin levels extend postmortem microscopy studies in schizophrenia that have found synaptic loss in the hippocampus and ACC by providing meta-analytic evidence consistent with loss of synapses between neurons." (PMID 29511299, 2019). "The synaptophysin decrease in the prefrontal cortex was demonstrated to be associated with a disruption in the balance between excitatory and inhibitory neurotransmission in schizophrenia." (PMID 37605213, 2023). "Some schizophrenia patients were found to have rare SYP mutations." (PMID 34659328, 2021). "Interestingly, the brain areas we found to have lower synaptophysin levels are among the regions that show the most volume loss in schizophrenia." (PMID 29511299, 2019). "Our findings of moderate–large reductions in synaptophysin in hippocampus and frontal cortical regions, and a tendency for reductions in other pre- and postsynaptic proteins in the hippocampus are consistent with models that implicate synaptic loss in schizophrenia." (PMID 29511299, 2019). "Post-mortem studies have reported lower levels of a number of pre-synaptic markers in schizophrenia relative to controls, with moderate-to-large effect size lower levels of synaptophysin in the frontal cortex, cingulate cortex and hippocampus on meta-analysis." (PMID 37041418, 2023). "In turn, deficits in the synaptic molecule synaptophysin, and in the synapse stabilizing structures perineuronal nets have been reported in the amygdala of subjects with schizophrenia." (PMID 37928499, 2023). "The SV2A PET imaging in schizophrenia thus extends post-mortem findings of lower protein and mRNA levels of synaptophysin and other presynaptic markers in samples from patients in these regions." (PMID 36056106, 2023). "Synaptophysin was significantly reduced in the CC of patients with schizophrenia with an ES of −0.54 (z = −2.35; 95% CI = −0.99, −0.09; p = 0.02)." (PMID 29511299, 2019). "A sub-analysis removing this study shows that there still is a significant reduction in synaptophysin levels in the ACC in schizophrenia relative to controls (ES = −0.61; z = −2.27; 95% CI = −1.14, −0.08; p = 0.02)." (PMID 29511299, 2019). "Thirteen studies comprising 170 patients with schizophrenia and 169 healthy controls measured synaptophysin levels in frontal cortical regions (approximating Brodmann Areas 9, 10, 46, 47)." (PMID 29511299, 2019). "Our main findings are that protein levels of the synaptic marker synaptophysin are significantly decreased in schizophrenia in the hippocampus and cingulate cortex." (PMID 29511299, 2019). "Seven studies (comprising 115 patients with schizophrenia and 105 healthy controls) measured synaptophysin in the CC (approximating BAs 24, 32, 33)." (PMID 29511299, 2019). "Eight studies (111 patients with schizophrenia and 106 healthy controls) measured synaptophysin levels in the hippocampus (CA1–4 and Dentate Gyrus)." (PMID 29511299, 2019). "Synaptophysin was significantly reduced in patients with schizophrenia with an ES of −0.36 (z = −2.05; 95% CI = −0.70, −0.02; p = 0.04)." (PMID 29511299, 2019). "Protein levels of synaptophysin were significantly reduced in schizophrenia subjects compared with controls (−27.84%; t36=−3.558, P=0.001)." (PMID 27430010, 2016). "Moreover, a recent meta-analysis focused on synaptic protein changes in schizophrenia revealed the decreased expression of synaptophysin (SYP) in the DLPFC and cingulate cortex." (PMID 39068467, 2024). "With regards to mRNA data for synaptophysin in the frontal cortex, one study reports a significant reduction in schizophrenia, while one reports a significant reduction in BAs 17 and 22 and a non-significant reduction in BAs 9 and 46, and two studies suggest no change in frontal cortex." (PMID 29511299, 2019).